TCN1 (transcobalamin 1)
Diseases named in the same sentence as TCN1 in open-access papers (continued):
Sharing a sentence is not in itself a finding about the gene and the disease.
TCN1 also shares sentences with these, for which no sentence is quoted: infection (3 papers); adenoma (2); breast phyllodes tumor (2); cholangiocarcinoma (2); acute myeloid leukemia (1); Autoimmune Thyroiditis (1); brain disorder (1); breast invasive carcinoma (1); colon adenocarcinoma (1); Diabetes (1); diffuse large B-cell lymphoma (1); endometriosis (1); folate deficiency (1); head and neck squamous cell carcinoma (1); hypopharyngeal squamous cell carcinoma (1); infectious disease (1); leukemia (1); lung squamous cell carcinoma (1); lymphoid neoplasm (1); lymphoma (1); mental disorder (1); metastasis (1); neurological disorders (1); pneumonia (1); testicular germ cell tumor (1); uterine corpus endometrial carcinoma (1).